CX3CR1 (C-X3-C motif chemokine receptor 1)
Diseases named in the same sentence as CX3CR1 in open-access papers (continued):
Sharing a sentence is not in itself a finding about the gene and the disease.
Klebsiella Infections (1 paper, 2026). Infections with bacteria of the genus KLEBSIELLA. "The expression of CX3CR1 on NK cells could be a potential biomarker and target for the treatment of septic patients with Klebsiella infection in the future." (PMID 41532069, 2026).
knee osteoarthritis (1 paper, 2025). "While an expression correlation analysis of clinical samples has identified CX3CL1 as a potential biomarker for knee osteoarthritis, its receptor CX3CR1 remains unreported in this regard, suggesting a gap that merits further investigation." (PMID 41007174, 2025).
left ventricular hypertrophy (1 paper, 2025). Enlargement of the LEFT VENTRICLE of the heart. "Building on our recent findings in CX3CR1-deficient mice, we postulate that early pro-inflammation may confer a cardioprotective effect in the development of left ventricular hypertrophy due to pressure overload." (PMID 40257974, 2025).
leishmaniasis (1 paper, 2019). Infectious disease that is transmitted through the bite of hematophagous female phlebotomine sand flies. "Leishmaniasis induced significant increase of spinal cord GFAP, Iba-1, TNF-α, IL-1β, CX3CR1, and CX3CL1 mRNA expression, which were inhibited by α-aminoadipate, minocycline, and PDTC treatments (p < 0.05)." (PMID 31138231, 2019).
liver cancer (1 paper, 2025). An epithelial or non-epithelial malignant neoplasm that arises from the liver. "NKG2D-CAR-T co-expressing CX3CR1 reduces tumor burden and extends survival in a liver cancer model, compared with control T cells or IL-15-overexpressing NKG2D CAR-Ts." (PMID 40612946, 2025).
Liver cirrhosis (1 paper, 2021). "Liver cirrhosis was induced by 8 weeks of CCl4 administration in CX3CR1-EGFP mice, followed by administration of PBS (vehicle), 5 μg AD-MSC-sEVs, and 5 μg AD-MSC-γ-sEVs after 24 h." (PMID 33785758, 2021).
Lymphadenopathy (1 paper, 2025). Enlargement (swelling) of a lymph node. "To explore the possibility that CX3CR1+ T cells in patients with LORA might undergo differentiation in the lymph nodes and subsequently migrate into the peripheral blood and synovial tissues, we investigated whether lymphadenopathy could be observed in patients with LORA." (PMID 39910629, 2025).
lymphopenia (1 paper, 2019). Reduction in the number of lymphocytes. "We identified a specific CHIKV signature composed of 107 down-regulated genes that includes CX3CR1, BTLA, BCL2, GZMK and three genes that encode Fc receptor-like glycoproteins that could be related to the lymphopenia induced by CHIKV infection." (PMID 31211814, 2019).
MALT lymphoma (1 paper, 2015). An indolent, extranodal type of non-Hodgkin lymphoma composed of small B-lymphocytes (centrocyte-like cells). "In comparing gastric to extragastric MALT lymphomas, the upregulation of CXCR1 and CXCR2 accompanied by downregulation of CCR8 and CX3CR1 and loss of XCR1 expression in extragastric MALT lymphomas appear to be key determinants for the site of origin of MALT lymphomagenesis." (PMID 25922601, 2015).
Marfan syndrome (1 paper, 2025). A disorder of the connective tissue. "Aortic CX3CR1+ macrophages derived from circulating monocytes mediate thoracic aortic aneurysm formation in Marfan syndrome by paracrinally causing vascular smooth muscle cell inflammation." (PMID 39817456, 2025).
mastitis (1 paper, 2025). Inflammation of breast tissue during lactation or postpartum due to an obstructed duct or infection. "In contrast, introgressed regions contained STAT5A and CSF3, both associated with mastitis resistance in cattle, and genes (CX3CR1 and CSF3) and QTLs involved in immune response and parasite resistance." (PMID 41273432, 2025).
medulloblastoma (1 paper, 2015). A malignant, invasive embryonal neoplasm arising from the cerebellum. "When hAT-MSCs were co-cultured with medulloblastoma-BTICs, the expression levels of CCR4, CCR5, CCR7, XCR1, CXCR1, CXCR4, PDGFR-bb, KDR and TEK were increased, while the levels of CX3CR1, IL1R, IL6R, IL8R, IGF1R and CD44 were decreased (p<0.05)." (PMID 26076490, 2015).
metastatic tumors (1 paper, 2013). "We observed that CX3CR1 deficiency significantly promoted macrophage apoptosis in the tumor microenvironment both in vivo and in vitro, which indicates that CX3CR1 deficiency inhibits macrophage infiltration in metastatic tumors through induction of macrophage apoptosis." (PMID 24245985, 2013). "To investigate the mechanism by which CX3CR1 promotes macrophage infiltration into metastatic foci, we analyzed macrophage apoptosis in metastatic tumors." (PMID 24245985, 2013). "Both the number of TUNEL- and F4/80-positive (macrophage marker) cells was significantly increased in metastatic tumors in CX3CR1−/− mice compared with those in WT mice." (PMID 24245985, 2013). "As expected, CX3CR1 promoted the survival of macrophages in metastatic tumors through suppression of the proapoptotic pathway." (PMID 24245985, 2013). "To further explore the relationship between CX3CR1 expression in macrophages and tumor angiogenesis, we assayed the proangiogenic function of macrophages from metastatic tumors." (PMID 24245985, 2013). "In particular, the proportion of infiltrating CD45+F4/80+ cells in metastatic tumors was significantly lower in CX3CR1−/− mice than that in WT mice (31.22 ± 2.10% versus 51.79 ± 2.66% for CD45+F4/80+ cells, P<0.01)." (PMID 24245985, 2013). "Livers from CX3CR1−/− mice showed significantly smaller tumor foci, fewer metastatic tumors, and decreased tumor-occupied area compared with those from tumor-bearing WT mice." (PMID 24245985, 2013). "Furthermore, our data demonstrated that CX3CR1 deficiency suppressed macrophage expression receptors CCR2, VEGFR2, and CXCR4 (cell surface markers of angiogenic macrophages) in hepatic metastatic tumors." (PMID 24245985, 2013). "Thus, CX3CR1 plays an important role in promoting macrophage infiltration in metastatic tumors." (PMID 24245985, 2013). "Immunofluorescence staining showed that CX3CR1 was abundantly expressed in macrophages in hepatic metastatic tumors of WT mice; as expected, there was no CX3CR1 expression in CX3CR1−/− control mice." (PMID 24245985, 2013).
myelodysplastic syndrome (1 paper, 2021). A clonal hematopoietic disorder characterized by dysplasia and ineffective hematopoiesis in one or more of the hematopoietic cell lines. "Interestingly, studies on the expansion of MDSCs in the context of myelodysplastic syndrome (MDS), showed a high membrane expression of CX3CR1 and CXCR4 on patients MDSCs compared to healthy controls and that these levels were correlated with patients’ risk stratification." (PMID 33922612, 2021).
myocardial ischemia (1 paper, 2025). A disorder of cardiac function caused by insufficient blood flow to the muscle tissue of the heart. "T lymphocytescontribute significantly to myocardial ischemia/reperfusion injury after primaryPCI (pPCI), with the fractalkine receptor CX3CR1 playing a pivotal role in thisprocess." (PMID 40160591, 2025).
ocular hypertension (1 paper, 2020). Abnormally high intraocular pressure. "In an acute model of ocular hypertension (perfusion of the anterior chamber with a hypertonic saline solution), it was shown that deletion of the Fractalkine receptor (CX3CR1) in KO mice reinforced microglial neurotoxicity and induced greater loss of RGCs." (PMID 32106630, 2020).
optic nerve glioma (1 paper, 2015). A glioma that affects the optic nerve. "Loss of one copy of the Cx3cr1 gene has been shown to reduce accumulation of microglia (by 50%) and delay optic nerve glioma development." (PMID 25987130, 2015).
ovarian teratoma (1 paper, 2013). A non-seminomatous germ cell tumor arising from the ovary. "The goal of this study was to determine a predominant cell type expressing fractalkine receptor (CX3CR1) in mature ovarian teratomas and to establish functional significance of its expression in cell differentiation." (PMID 23958497, 2013). "Cases of tested immature ovarian teratoma were characterized by the presence of CX3CR1-positive brain, lymphatic, respiratory epithelial, adipose, and sebaceous cells." (PMID 23958497, 2013). "According to our previous observations CX3CR1 was expressed in cells comprising ovarian teratoma tissue specimens, although the number of specimens was very limited in order to be able to draw any conclusions." (PMID 23958497, 2013). "The goal of this study was to determine the predominant type of CX3CR1-positive cells in ovarian teratomas." (PMID 23958497, 2013). "Our previous data obtained using a limited number of subjects suggested that a chemokine receptor fractalkine (CX3CR1) is expressed in ovarian teratomas." (PMID 23958497, 2013). "In the present study we aimed to expand this observation on a larger number of ovarian teratoma specimens and determine the predominant cell type(s) positive for CX3CR1." (PMID 23958497, 2013). "Our findings demonstrate that cells of the skin lineage comprise the most predominant CX3CR1-positive cell type within the specimens of ovarian teratoma." (PMID 23958497, 2013). "Here we demonstrate that CX3CR1 is expressed in both normally (fetal skin) and abnormally (ovarian teratoma) differentiated keratinocytes and is required for cell differentiation into epidermal lineage." (PMID 23958497, 2013). "Hence, CX3CR1-positive skin cells are present not only within abnormally differentiated tissues, such as mature ovarian teratomas, but also in the normally developing skin." (PMID 23958497, 2013). "Thus, we tested expression of CX3CR1 using a tissue microarray containing 68 specimens of mature ovarian teratoma, 10 specimens of immature teratoma, and 2 cases of monodermal teratoma." (PMID 23958497, 2013). "Thus, our data suggest that skin keratinocytes are the predominant type of CX3CR1-positive cells in the tested specimens of mature ovarian teratomas." (PMID 23958497, 2013).
ovarian tumor (1 paper, 2011). "Finally, our data are consistent with a model in which GILZ activates CX3CL1 and the chemokine acts alone to support ovarian tumor cell proliferation via CX3CR1." (PMID 21750716, 2011).
pituitary tumor (1 paper, 2024). A benign or malignant neoplasm affecting the pituitary gland. "Clinically, INHBA agonists can promote the INHBA-ACVR1B pathway to eliminate SF1 lineage pituitary tumors or increase the infiltration of CX3CR1+ macrophages in other lineages, helping PitNET treatment." (PMID 38658971, 2024).
post-traumatic stress disorder (1 paper, 2021). An anxiety disorder precipitated by an experience of intense fear or horror while exposed to a traumatic (especially life-threatening) event. "In addition, CX3CR1-deficient (CX3CR1−/−) mice elicited increased fear acquisition as well as reinstatement of fear, which are related to post-traumatic stress disorders." (PMID 34683104, 2021).
pulmonary embolism (1 paper, 2018). The obstruction of the pulmonary artery or one of its branches by an embolus, sometimes associated with infarction of the lung. "Our previous studies have reported that CX3CL1, CX3CR1, and NF-κB are significantly increased after pulmonary embolism, and NF-κB signaling pathway and CX3CL1/CX3CR1 are perhaps directly involved in the whole inflammatory response of pulmonary embolism." (PMID 30671487, 2018).
pulmonary tuberculosis (1 paper, 2025). A bacterial infection that affects the lungs and is caused by Mycobacterium tuberculosis. "We found that the combined loss of Ccr2 and Cx3cr1 also worsened Mtb control in the mediastinal lymph node, suggesting a rationale for the persistent expression of CX3CR1 among monocyte-derived cells in pulmonary tuberculosis." (PMID 40497732, 2025).
Rb (1 paper, 2019). "This is the first study suggesting that these genes, FGFR4, NQO1, ACADS CX3CR1, GBE1, KRT85, and TYR genes, may play a role in the etiology of Rb." (PMID 31207142, 2019).
relapsing-remitting MS (1 paper, 2018). "CX3CR1+CD4+ T cells were enriched in cerebrospinal fluid of relapsing-remitting MS patients and CX3CR1 appears critical for the development of CD8 memory T cells." (PMID 30386211, 2018).
Retinal atrophy (1 paper, 2013). A nonspecific term denoting wasting, especially as a result of degeneration, of the retinal pigment epithelium (RPE) and neurosensory retinal cells. "Since our mice do not have Crb-1 rd8 mutation, our results suggest that the deletion of Ccl2 and Cx3cr1 predisposes mice to retinal atrophy under aging and chronic light damage conditions more so than in the single CCL2 or CCR2 knockout mice." (PMID 23637822, 2013).
Retinal dysplasia (1 paper, 2022). Abnormal growth and differentiation, structure and appearance of the retina present from birth. "Cx3cr1, Mthfr, and Cygb were identified as modifiers of Crb1rd8 retinal dysplasia, Jak3 as an enhancer of a Crb1rd8-dependent neovascular phenotype, and Crb2 as a modifier of retinal dysplasia due to a Crb1 knock-out allele." (PMID 35675330, 2022).
scoliosis (1 paper, 2025). A congenital or acquired spinal deformity characterized by lateral curvature of the spine. "SERPINH1 shared the same variant with CX3CR1 on CD14− CD16− which could increase the risk of scoliosis." (PMID 40177401, 2025). "In our MR analysis, we noted that the increased expression of CX3CR1 on CD14− CD16−, which shared the same variant with SERPINH1, and CCR2 on CD14− CD16−, which shared the same variant with FSD1L, was associated with an elevated risk of scoliosis." (PMID 40177401, 2025). "Basophil %CD33dim HLA DR− CD66b− (p-value, <0.001; OR, 1.203; 95%CI, 1.08−1.34), CX3CR1 on CD14− CD16− (p-value, 0.006; OR, 1.297; 95%CI, 1.078−1.562), and CCR2 on CD14− CD16− (p-value, 0.002; OR, 1.478; 95%CI, 1.157−1.889) could increase the risk of scoliosis." (PMID 40177401, 2025). "Controlling the balance between CX3CR1 and SERPINH1 may be beneficial for intervention in scoliosis." (PMID 40177401, 2025). "We hypothesized that CX3CR1 may inhibit the function of SERPINH1, which could result in immune disorders and, ultimately, scoliosis." (PMID 40177401, 2025).
septic arthritis (1 paper, 2025). "The released CGRP then inhibits the production of chemotactic cytokines by CX3CR1+ tissue-resident synovial lining macrophages via receptor activity modifying protein 1 (RAMP1) receptors at the onset of septic arthritis." (PMID 39960341, 2025).
serous ovarian cystadenocarcinoma (1 paper, 2018). "MYC mRNA expression correlated with expression of CX3CR1 in specimens of serous ovarian cystadenocarcinoma." (PMID 29712888, 2018).
Shock (1 paper, 2016). The state in which profound and widespread reduction of effective tissue perfusion leads first to reversible, and then if prolonged, to irreversible cellular injury. "In addition, this study validates, in a large cohort of patients, our previous results showing that decreased CX3CR1 mRNA is an independent predictor of death after septic shock." (PMID 27364780, 2016).
skin inflammation (1 paper, 2020). "In an AD model induced by epicutaneous sensitization with Leishmania major-activated C kinase, CX3CR1 expressed by CD4+ T cells contributed to their retention into the inflamed skin and exacerbation of dermatitis." (PMID 33036460, 2020).
skin sensitization (1 paper, 2025). An immunological response to previous exposure to a substance which results in an inflammatory skin reaction. "In the context of skin sensitization, dermal DCs and/or CX3CR1 DCs play a role in allergen delivery to LNs and spleen, and IL-13 has a selective role in providing the activation signal for cDC2s to increase antigen-presenting capacity and promote robust IgE responses via memory Th2 and TFH2 cells." (PMID 39989951, 2025).
spinal cord injury (1 paper, 2017). Penetrating and non-penetrating injuries to the spinal cord resulting from traumatic external forces (e.g., WOUNDS, GUNSHOT; WHIPLASH INJURIES; etc.). "Apart from the role under physiological conditions, the CX3CL1/CX3CR1 axis was implied to have a role in different neuropathologies such as traumatic brain injury (TBI) and spinal cord injury (SCI)." (PMID 26927660, 2017).
ST Elevation Myocardial Infarction (1 paper, 2021). A myocardial infarction that produces elevation in the ST segments of the ECG. "We investigated the role of CX3CR1 (fractalkine receptor) in CMV-related lymphocyte kinetics and cardiac remodeling in patients with ST-elevation myocardial infarction (STEMI) undergoing primary percutaneous coronary intervention (pPCI)." (PMID 34046028, 2021).
synovitis (1 paper, 2025). Inflammation of a synovial membrane. "In the present study, we found that CX3CR1+CD4+ T cells contribute to synovitis in LORA." (PMID 39910629, 2025).
syphilis (1 paper, 2020). A contagious bacterial infection caused by the spirochete Treponema pallidum. "Currently, the dynamic changes of CCR2 and CX3CR1 on monocyte subsets during HIV-1 and syphilis coinfection have not been fully investigated." (PMID 32626718, 2020).
T-cell lymphomas (1 paper, 2021). "Here we report that Cx3cr1-dependent combined ablation of Hdac1 and Hdac2 leads to delayed maturation of T-cell precursors and to development of T-cell lymphomas." (PMID 33849645, 2021). "Furthermore, we report that these mice develop a T-cell neoplasia at about 4–5 months of age, suggesting that a Cx3cr1 expressing subpopulation of immature T-cells gives rise to T-cell lymphomas in the combined absence of Hdac1 and Hdac2." (PMID 33849645, 2021).
tendinopathy (1 paper, 2019). "Given the role in cell proliferation, angiogenesis and fibrosis upon inflammation, and considering that they are hallmarks of tendinopathy, targeting the CX3CL1/CX3CR1/EREG axis could potentially open up new vistas in tendinopathy therapy." (PMID 31744815, 2019).
teratoma (1 paper, 2013). A non-seminomatous germ cell tumor characterized by the presence of various tissues which correspond to the different germinal layers (endoderm, mesoderm, and ectoderm). "Two tested monodermal teratomas consisted of CX3CR1-positive thyroid and lymphatic tissues, respectively." (PMID 23958497, 2013). "Thus, the studies of the role of CX3CR1 in keratinocyte differentiation need to be expanded further to include more extensive studies on other abnormally differentiating teratoma cell lines, as well as normally differentiating embryonic stem cells." (PMID 23958497, 2013).
Trypanosoma cruzi infection (1 paper, 2025). "Altogether, there remains a promising avenue of investigation into the inhibition of the CX3CR1/CX3CL1 axis in the context of Chagas disease." (PMID 40936920, 2025).
varicocele (1 paper, 2017). A condition characterized by the dilated tortuous veins of the spermatic cord with a marked left-sided predominance. "Our results show a significant increase in MDA and TAC levels, DNA fragmentation, and expression levels of fractalkine and its receptor (CX3CR1) in subclinical varicocele groups." (PMID 29527225, 2017).
vitiligo (1 paper, 2021). Generalized well circumscribed patches of leukoderma that are generally distributed over symmetric body locations and is due to autoimmune destruction of melanocytes. "Some cytokines such as KLRG1+ lymphocytes secrete cytotoxic molecules (granzyme B and perforin), inflammatory cytokines (IFN-γ and TNF-α), and inflammatory chemokine receptors (CCR5 and CX3CR1) are involved in gene expression, which are associated with vitiligo." (PMID 33679890, 2021).